PTPRC (protein tyrosine phosphatase receptor type C)
Diseases named in the same sentence as PTPRC in open-access papers (continued):
Sharing a sentence is not in itself a finding about the gene and the disease.
primary immunodeficiency (2 papers, 2023 to 2025). "In this study, we have identified four enriched crosstalk genes in primary immunodeficiency, Interferon type I signalling, and translation factors pathways; that is, LCK, PTPRC, EIF4A1, and EIF4EBP1." (PMID 37277696, 2023). "Our results revealed significant associations between specific metabolites and genes, indicating that low-concentration exposure to BHPF affects endometrial epithelial cells by targeting pathways related to primary immunodeficiency, in which the key genes are IL7R and PTPRC." (PMID 39997915, 2025).
pulpitis (2 papers, 2020 to 2024). Inflammation of the dental pulp. "PTPRC is expressed at low levels in normal dental pulp tissue but at high levels in pulpitis tissue." (PMID 33046027, 2020). "The expression level of PTPRC was low in normal pulp tissues but high in pulpitis tissues." (PMID 39346909, 2024). "In addition to investigating the possible regulatory mechanisms of DEGs, we screened key genes as biomarker candidates for the diagnosis of pulpitis, including PTPRC, CD86, CCL2, IL6, TLR8, MMP9, CXCL8 and ICAM1." (PMID 33046027, 2020).
biliary tract cancer (1 paper, 2017). "Besides the mutation in MSH6, we identified 3 more mutations affecting genes described in cancer, but only rarely reported in biliary tract cancer (≤ 2%; SRC, MSN, PTPRC)." (PMID 28146430, 2017).
diverticulitis (1 paper, 2024). An infection that develops in the diverticula of the intestinal tract. "Hub genes RASAL3, SASH3, PTPRC, and INPP5D were found to upregulate immune response-associated transcripts in the sigmoid colons of chronic, recurrent diverticulitis patients as identified by Schiefer et al25." (PMID 38831715, 2024). "PTPRC (CD45) encodes a cell-surface glycoprotein involved in protein tyrosine phosphorylation, in particular the initiation of leucocyte-specific immune responses resulting in high levels of inflammatory cytokines which may play a role in the chronicity of diverticulitis." (PMID 38831715, 2024). "This built on earlier work, by the same team, which suggested the hub genes RASAL3, SASH3, PTPRC and INPP5D within the brown module eigengene were highly correlated (r = 0.67, P = 0.0004) with diverticulitis." (PMID 38831715, 2024).
ependymoma (1 paper, 2023). A WHO grade II, slow growing tumor of children and young adults, usually located intraventricularly. "Protein Tyrosine Phosphatase Receptor Type C (PTPRC) gene, also known as CD45, was above the detection limit in all samples by NanoString and RNA sequencing, which reflects leukocytes infiltrated into the ependymoma tumor." (PMID 37072536, 2023).
immunotoxicity (1 paper, 2020). "Five genes (CD8A, CYP1A1, ITGAX, LYZ, and PTPRC) associated with immunotoxicity were among the most up‐regulated genes exposed to dose 1:8 indoor PM." (PMID 31883508, 2020).
pneumococcal pneumonia (1 paper, 2016). A febrile disease caused by STREPTOCOCCUS PNEUMONIAE. "We identified ERM complex, PGLYRP1, PTPRC/CD45 and POSTN as new players in the pathogenesis of pneumococcal pneumonia." (PMID 27247105, 2016).
tumor (3,178 papers, 1989 to 2026). "Trogocytosis between T cells and TNBC cells altered tumor cell expression of PTPRC, the gene that encodes for CD45." (PMID 40183054, 2025). "On the other hand, canine tumor NK cells had increased expression of PTPRC/CD45, a hallmark present on all leukocytes, which had a high probability of interaction with MRC1 on myeloid cells in the canine lung." (PMID 41208961, 2025). "In SCLC data sets, low NE-score samples exhibited upregulation of MHC I genes and were associated with higher PTPRC expression in patient tumor data sets." (PMID 33750914, 2021). "It was also found that a higher percentage of tumor occupied by PTPRC+ cells was strongly associated with enhanced tumor-infiltration by Tbet+ cells and Foxp3+ cells." (PMID 31740624, 2019). "Specifically, in the tumor from patient #7, genes involved in T cell activation and signaling such as PTPRC (which encodes CD45), LCP2, FYB, CD3E, and LCK, and in genes involved in immune response and interferon signaling such as STAT1, OAS2, and HLA were downregulated." (PMID 37620318, 2023). "Furthermore, we identified PTPRC as a pivotal ICG-associated tumor driver gene (ICD-TDG) in regulating the CD8+ T cell infiltration-mediated anti-tumor effect." (PMID 37388747, 2023). "The expression levels of IL7R, IRF8, and PTPRC were significantly upregulated in recurrent tumors, compared with primary tumors, and correlated strongly with one another across both tumor types (p < 0.05)." (PMID 41596598, 2026). "We further investigated and analyzed the EPCs subtypes, categorizing them into C0 TSPAN1+ Tumor EPCs, C1 AKR1B10+ Tumor EPCs, C2 TOP2A+ Tumor EPCs, C3 PTPRC+ Tumor EPCs, and C4 LRMP+ Tumor EPCs." (PMID 40777026, 2025). "The PTP(protein tyrosine phosphatase) family members encoded by the PTPRC gene have complex dual roles in tumor biology: on the one hand, they can act as tumor suppressors, preventing tumor progression; on the other hand, they may also act as oncogenes, promoting tumor development." (PMID 41411247, 2025). "First, we analyzed the distribution of tumor (EpCAM+) and immune (PTPRC/CD45+) cells within the tumor tissue, confirming that these 2 cell populations were largely nonoverlapping." (PMID 41376815, 2025). "Surveying the Xenium probe-based in situ sequencing and imaging data, we found high agreement between three cell type markers (ERBB2-tumor, PTPRC-immune, and PDGFRA-stroma) and our CTA outcomes, suggesting its robustness for detecting FFPE sections as well." (PMID 40925915, 2025). "Other proteins that also showed increased expression in tumor tissue are Protein Tyrosine Phosphatase Receptor Type C (PTPRC) and Toll-Like Receptor 2 (TLR2)." (PMID 36615183, 2023). "KRT19 (tumor epithelial cells), PTPRC (CD45; immune/hematopoietic cells), and PDGFRB (stromal cells) were highly expressed by cells in different clusters." (PMID 37966117, 2023). "The protein tyrosine phosphatase receptor type C (PTPRC) encoded CD45, which correlates with the stemness of CRC cells, was increased in remnant tumour tissues after expression in both 5-FU-treated and irradiated CRC cells." (PMID 36766788, 2023). "A total of five potentially targetable tumor antigens were identified (PTPRC, SIGLEC10, CARD11, LILRB1, ADAMDEC1); high antigen expression was associated with prolonged OS and DFS, as well as higher tumor infiltration by antigen-presenting cells." (PMID 36992220, 2023). "The results showed that LTB and PTTG1 genes were significantly up-regulated in tumor tissues, while PTPRC expression was increased in normal tissues." (PMID 37671160, 2023). "Tumor immune cells (PTPRC/CD45+) also consisted of B cells (MS4A1/CD20+), plasma cells (XBP1+), macrophages (CD14+), dendritic cells (CD80+, CD86+), and mast cells (TPSAB1+)." (PMID 35742914, 2022). "We confirmed the restriction of SOX2 expression to tumor cells, PTPRC/CD45 to immune cells, SPI1/PU.1, CD68, and CD163 to ‘macrophages’, CD3G to ‘T cells’, and OLIG1/2 and MBP to oligodendrocytes." (PMID 35973991, 2022).
tumor (continued). "Examining CoMMpass data, we confirmed both CD33 and PTPRC transcripts to be significantly increased at first relapse vs. diagnosis in patient tumor cells." (PMID 35840578, 2022). "In another study, the inhibition of PTPRC reduced the rates of tumour growth and metastasis in vivo." (PMID 35286517, 2022). "It has been suggested that PTPRC, as an adhesion molecule, is involved in the spread of the tumour and immortalisation of the tumour cells during malignancy." (PMID 35286517, 2022). "For the validation of this analysis, the GEPIA expression level of the hub genes were also employed and gene- ITGAM, ITGAX, PTPRC along with STAT3 were found in lower expression levels in tumor cells." (PMID 33946372, 2021). "Further study analysised by CIBERSORT algorithm showed many tumor infiltrating immune cell were correlated with the expression of PTPRC." (PMID 33520448, 2021). "Longer disease-free and disease-specific survival were reported in the type I-oriented PTPRC+ cell to infiltrate occupied tumor areas." (PMID 33946372, 2021). "In the low expression level of PTPRC, the genes were basically enriched in glycolysis, and typical tumor pathway including MYC-targets-V1 and MYC-targets-V2." (PMID 33520448, 2021). "Elevated expression level of FYN (p value = 0.000), LCP2 (p value = 0.002), PTPRC (p value = 0.011), WAS (p value = 0.005), ZAP70 (p values = 0.000) and NCF4 (p values = 0.047) were associated with tumor size." (PMID 34834481, 2021). "Compared to controls, tumor displaying lower SNAI1, PECAM1 and VIM and higher TP63, KRT14, KRT5 and PTPRC (CD45) RNAs (PyMT-VE-CadhSnail1KO tumor signature) presented a longer overall survival, strengthen our mice results." (PMID 34335957, 2021). "The expression level of PTPRC in tumor tissues of female LUAD patients was lower than that in normal tissues (p < 0.05), and female LUAD patients with high level of PTPRC exhibited a better overall survival (p = 0.006)." (PMID 34863300, 2021). "T and tumor cells were identified by the expression of classic cell type markers, including PTPRC, CD3G, CD3E, TRBC1, and CD8B for T cells and MAGEA 4 for MEL-526 cells." (PMID 33754038, 2021). "PTPRC, as a transmembrane tyrosine phosphatase, is expressed in all leukocytes, and it is involved in lymphocyte immunity against tumor cells." (PMID 32457603, 2020). "To investigate this, we analyzed the correlations between well-known immune and tumor cell markers (CD45 or PTPRC, CD3, CD8, etc and CDH1, EPCAM) with ISGF3 subunits within the TCGA dataset." (PMID 30355451, 2018). "Especially, LIM (kinase) domain containing 2 (LIMD2) and the protein tyrosine phosphatase receptor type C (PTPRC also known as CD45) were significantly different expressed in tumor samples versus metastatic samples." (PMID 20671939, 2010). "Similarly, in hematologic malignancies such as AML, PTPRC promotes tumor growth by localizing to lipid rafts, where it enhances GM-CSF signaling through the activation of Src family kinases." (PMID 41596598, 2026). "Functional validation further demonstrated that IL7R, IRF8, and PTPRC contribute to tumor progression by promoting immune evasion, whereas NSG1 might have tumor-suppressive effects." (PMID 41596598, 2026). "Much like the acquisition of protein through trogocytosis, it is still unclear whether tumor cells that acquire gDNA from T cells sustain transcription of immune cell genes such as PTPRC." (PMID 40183054, 2025). "Moreover, the expression of the critical downstream mediator of IRE1α pathway, XBP1, was also highly associated with the mRNA levels of the indicators of lymphocytes and anti-tumor immunity, including PTPRC (encoding CD45), CD8A, GZMB and IFNG." (PMID 38291473, 2024). "In our study, we verified that LTB and PTTG1 were highly expressed in tumor tissues and PTPRC was highly expressed in normal tissues using clinical surgical resection samples, but further mechanistic experiments are needed to verify the specific functions of these model genes." (PMID 37671160, 2023).
tumor (continued). "Besides, down-regulation of PTPRC lead down-regulation of tumor-derived IL2 and up-regulation of tumoral PD-L1." (PMID 37388747, 2023). "The expression levels of CD69, IL7R, and PTPRC decreased with the progression of tumor stages." (PMID 36032150, 2022). "In the tumor periphery, PTPRC+CD68+ immune cells expressed P2RY12, a marker of microglia." (PMID 36266311, 2022). "To ensure that the influence of our TEX signature was associated with survival independently of overall immune and T cell infiltration, we also included gene expression of CD8A, CD3G, and PTPRC in addition to patient age, tumor grade, tumor size, and LN status." (PMID 35132960, 2022). "In dataset GSE9008, resveratrol treatment increased mRNA level of PTPRC in A549 cells, which could be the potential target of resveratrol inhibit tumor progress." (PMID 34633989, 2021). "All of these result suggest PTPRC participating in tumor microenvironment, and could be an indicator of TNM status." (PMID 33520448, 2021). "We next performed unsupervised hierarchial clustering using expression of lineage marker genes and genes encoding candidate immunosuppressive functions, which identified two main groups: non‐immune (comprising tumour and neuronal cells) and immune cells (PTPRC+)." (PMID 31784984, 2020). "To explore whether SpatialSNV is able to identify essential SNVs in tumorigenesis, we utilized transcriptomics data to divide the tumor section into the tumor (marked by EPCAM and other tumor-associated markers), tumor-adjacent margins (marked by VIM, COL1A2, PTPRC), and normal tissues." (PMID 40515555, 2025). "However, as the patient tumor datasets contain a wide variety of cell types including immune, endothelial, and fibroblast cells, these cells were first removed from our analysis based on the expression of PTPRC (CD45), ESM1, and TAGLN respectively." (PMID 40241258, 2025). "In conclusion, we identified novel recurrently mutated genes in T-PLL, including PTPRC, regulating the JAK/STAT pathway, epigenetic regulators like PRDM2 and HERC1/2, and genes involved in DNA damage response and DNA repair like SAMHD1, which has most likely a tumor-suppressor function in T-PLL." (PMID 29352181, 2018). "In recurrent HGSOC, the recurrent tumor-specific DEGs IL7R, IRF8, and PTPRC displayed significant correlations with seven proteins." (PMID 41596598, 2026). "the that correctly localized PTPRC to immune areas and SPINK1 to the tumor boundary, aligning with pathology annotations." (PMID 40162205, 2025). "Specifically, ALB and CYP2E1 were highly expressed in normal areas, GPC3 and AKR1B10 were highly expressed in tumor areas, ACTA2 and COL1A1 were highly expressed in fibrostic areas, and PTPRC was highly expressed in inflammation areas." (PMID 40051627, 2025). "Thor correctly localized PTPRC to immune areas and SPINK1 to the tumor boundary, aligning with pathology annotations." (PMID 40764306, 2025). "Tumor cells were identified using SDC1 as a marker, while immune cells were characterized using PTPRC." (PMID 40376263, 2025). "The 11 coupregulated factors included PTPRC (a positive regulator of T-cell activation), IFI16 (a hematopoietic differentiation modulator), and SMARCE1 (a chromatin remodeler that enhances tumor suppressor accessibility)." (PMID 41304891, 2025). "The canonical markers EPCAM and KRT19 identified tumor cells, while CD3D, CD2, PTPRC, CD14, AIF1, CD79A, and COL1A2 validated non-tumor cells." (PMID 39955556, 2025). "The modulation of PTPRC (CD45) suggests enhanced leukocyte activity, which is vital for initiating and sustaining an anti-tumor immune response." (PMID 40260377, 2025). "We locate human T cells as cells expressing high PTPRC, CD2, and TRAC and observe areas within the tumor with high variability in the degree of infiltration." (PMID 40081369, 2025). "We identified five tumor EPC subtypes using cell markers: C0 TSPAN1+, C1 AKR1B10+, C2 TOP2A+, C3 PTPRC+, and C4 LRMP+." (PMID 40777026, 2025).
tumor (continued). "Normal liver cells and tumor cells clusters were extracted for separate UMAP clustering and further classified by AFP, PTPRC, ALB, GPC3." (PMID 39015573, 2024). "In 2021, Thomas F Gajewski and colleagues reported that up to 90% of PTPRC+ cells produced CXCL10 transcripts, which played a critical role in recruiting effector CD8+ T cells to the tumor site." (PMID 38571962, 2024). "As the results showed, the down-regulation of PTPRC increased the tumoral (MBA-MD-231) expression of PD-L1 about 1.53-fold as compared to NC group, while the expression level of tumor-derived IL2 was down-regulated." (PMID 37388747, 2023). "LTB, PTPRC, and PTTG1 were significantly different between normal and tumor samples from TCGA-LUAD, whereas the other model genes were not." (PMID 37671160, 2023). "Our data indicated that the “cold” tumor types like MB and EPN also contained the major classical immune cells, such as T cells (PTPRC, CD3D), B cells (CD79A, IGHG1, MZB1), and NK cells (KLRB1)." (PMID 38094301, 2023). "The expression levels of IL7R, CD69, and PTPRC and the TNM stages of the tumor were significantly related to the OS rate of SKCM patients." (PMID 36032150, 2022). "The results showed that the expression of CD2, SPN, IL18, PTPRC, GZMA, and TLR7 was upregulated in the tumor group compared with the normal group (p < 0.05)." (PMID 36591509, 2022). "In this study, using RNA-seq data of 576 HCC patients, a panel of seven genes (including LCP2, TYROBP, ZAP70, PTPRC, FYN, WAS and NCF4) has been identified which are independent predictors of delayed tumor recurrence and improved patient prognosis." (PMID 34834481, 2021). "In this study, we investigated the transcriptomic and spatial characteristics of hybrid circulating tumor cell (CTC)-like cells co-expressing epithelial (KRT18) and immune (CD45/PTPRC) markers, termed KP_Pos, to elucidate their origin and clinical significance." (PMID 41355965, 2026). "Another study found that CD69 could serve as a prognostic marker for SKCM, influencing immune response through interactions with genes like PTPRC and IL7R, and impacting tumor progression by regulating the tumor immune microenvironment." (PMID 40547036, 2025). "Importantly, there were multiple ligand-receptor interactions within the same tumor-CD8 pairs, and among the recognized G9 interacting partners, PTPRC (CD45) that bears glycan chains, was likely to be the major counterpart." (PMID 39910335, 2025). "Furthermore, we performed Spatalk analysis to elucidate the spatial communication patterns between STMN2+ TAM, CD8+ Tex cells and Tem/Teffe cells in tumor sections, investigating the ligand-receptor interactions (LRIs) between LGALS1 and PTPRC." (PMID 41438751, 2025). "We found several molecules that are significant in tumor initiation and treatment by immune checkpoint analysis, such as lymphocyte-activation gene 3 (LAG3), PTPRC, HAVCR2, B2M, LDHA, and LDHB, which may be used as a reference for tumor immunotherapy." (PMID 39014082, 2024). "Furthermore, immunohistochemistry was performed on an immune cell marker (PTPRC/CD45), which found that the tumour region is immunosuppressed compared to the paratumoural region." (PMID 39548559, 2024). "Genes with expression that correlates well with the expression of PTPRC are likely to indicate the presence of the genes in WBCs rather than or in addition to their presence in tumor cells." (PMID 37365600, 2023). "Most of these cells were tumor epithelial cells, characterized by high expression of keratin 19 (KRT19) and low expression of PTPRC (CD45), PECAM1 (CD31), and PDGFRB, which are markers for immune/hematopoietic cells, endothelial cells, and stromal cells, respectively." (PMID 37966117, 2023). "Meantime, the tumor-derived IL6 and PD-L1 were down-regulated as the up-regulation of PTPRC." (PMID 37388747, 2023).